CXCL1 (C-X-C motif chemokine ligand 1)
Diseases named in the same sentence as CXCL1 in open-access papers (continued):
Sharing a sentence is not in itself a finding about the gene and the disease.
tumor (continued). "Western bolt analysis supports that blockade of B7‐H3 could effectively attenuate the recruitment of MDSCs and M2 macrophages by reducing chemokine CXCL1 and CCL2 in the tumour." (PMID 28401653, 2017). "Both blocking CXCL1/CXCR2 signaling pathway and depleting neutrophils decreased tumor burden." (PMID 29179487, 2017). "The CXCL1, CXCL5, and CXCL6 chemokines have the ELR motif proximal to the CXC sequence, and all ELR containing CXC chemokines have been shown to be potent promoters of tumor hemangiogenesis." (PMID 28624797, 2017). "In agreement with our findings, this analysis revealed no significant statistical differences in CXCL1 expression between tumor and adjacent non-tumor tissues (P = 0.441)." (PMID 27542259, 2016). "In malignant prostate epithelium, a high level of CXCL1 expression was observed for 19 out of 21 obese patients, irrespective of tumour grade." (PMID 27241286, 2016). "CXCL1/KC/GRO was shown to recruit and activate murine neutrophils and could modify tumor growth by numerous mechanisms." (PMID 27388564, 2016). "We found that Cxcl1 mRNA was elevated in tumours from obese mice but not in the NLRC4 inflammasome-dependent manner." (PMID 27708283, 2016). "Mice were SC grafted with control-sh-RM1 or CXCL1-sh-RM1 cells and were allowed to form tumours." (PMID 27241286, 2016). "Consistent with that notion, αSMA+ cells were abundant in control-sh-RM1 tumours, but not in CXCL1-sh-RM1 tumours grown in obese animals." (PMID 27241286, 2016). "Both the tumor volume and weight were lower in the mice that received CXCL1 siRNA compared with the negative control siRNA‐treated mice (tumor volume, 603.4 ± 60.8 mm3 vs. 1095.1 ± 102.1 mm3; tumor weight, 283.5 ± 21.3 mg vs. 492.5 ± 43.1 mg, respectively)." (PMID 27682863, 2016). "This unbiased approach identified CXCL1 as the only chemokine in the panel that circulated at more than a twofold higher level in obese animals, compared with non-obese animals bearing tumours." (PMID 27241286, 2016). "In order to verify the effect of CXCL1 on tumor progression, a xenograft tumor growth assay was performed by injecting nude mice with cells transfected with CXCL1 overexpression (Lv-CXCL1) or knockdown (Lv-shCXCL1) lentivirus or negative control (Lv-NC)." (PMID 27542259, 2016). "Furthermore, analysis of serum samples from MC38 tumour bearing mice also revealed a notable reduction in CCL2 levels, whereas serum levels of CXCL10 and CXCL1 were unaffected." (PMID 26358505, 2015). "Notably, the set of the most influential HSC regulators included several well-known tumor-promoting genes such as placental growth factor (PGF), and the chemokine CXCL1, which promotes HCC angiogenesis and growth." (PMID 26020769, 2015). "Chemokines CXCL1, CXCL2 and CXCL12 have been proved to play important roles in the growth of various cancers by activating MAPK/ERK signaling pathway and thus promote tumor cell proliferation." (PMID 26313265, 2015). "Taken together, our data provided compelling evidence that the CXCL1/2-CXCR2 signaling pathway contributes to SCC maintenance and that during tumor progression, it becomes activated through dramatic remodeling of the Cxcl1/2 locus from a PcG-repressed to an ETS-regulated, SE-activated state." (PMID 26590320, 2015). "Our observations that decrease CXCL1 secretion by SW620 cells inhibited their anchorage-independent and xenograft tumor growth are supported by similar findings in KRAS mutant LS174T CRC cells, whose malignant growth were inhibited by CXCL1 siRNA or neutralizing α-CXCL1 antibody." (PMID 26104296, 2015). "In 2015, le Rolle and colleagues found that CXCL1 overexpression is a poor prognostic marker on metastatic CRC, furthermore, CXCL1 inhibition could suppress tumor cell growth of KRAS mutant CRC cells." (PMID 26208990, 2015). "Inhibition of CXCL1 by neutralizing antibody and specific shRNAs decreased CRC tumor growth." (PMID 26104296, 2015).
tumor (continued). "These neutrophils may be able to kill the tumor cells in the first 24 hours and provoke release of CXCL1 and CXCL2 from the surrounding tissue, helping T-cells traffic to the tumor site." (PMID 24949488, 2014). "In our work, we found that NF-κB induced the expression of CXCL1, ICAM1 and TNFAIP3 after doxorubicin treatment only in a subset of tumors, suggesting that differences in responses may exist among tumor subtypes." (PMID 24344116, 2014). "CCL2, CXCL1, and IL6, produced by 18Co cells could contribute to increased STAT1 activity in tumor cells." (PMID 24818101, 2014). "Increased stromal CXCL1 protein expression did not significantly correlate with grade of DCIS, but was significantly associated with IDC tumor grade." (PMID 25344051, 2014). "The chemokine (C-X-C motif) ligand 1(CXCL1) is co-regulated by the NF-κB and STAT3 signaling, and its overexpression in dysplastic phases suggested that it may function as a tumor initiator." (PMID 25057912, 2014). "High, unique expression of chemokines including CXCL1, CXCL5, and IL8 in this tumor may therefore have tumor cell origins." (PMID 25155515, 2014). "Notably, Bcl-2 acts as a signaling molecule by activating the NF-kB signaling pathway and inducing expression of CXCL1 and CXCL8 that in turn enhance the invasive phenotype of neighboring tumor cells." (PMID 24391922, 2013). "In addition to affecting the biology of the tumor cells themselves, activation of PPARγ also reduced production of the tumor cell-derived cytokines CXCL8, CXCL5, and CXCL1, which are critical for angiogenesis and tumor-stromal interactions." (PMID 22934105, 2012). "Although CXCL1 expression has previously been detected in CRC epithelium, our analysis showed an additional correlation between CXCL1 and the expression of its biological target, the CXCR2 receptor within the tumour samples (P<0.001)." (PMID 21285972, 2011). "The CXCL1 and its receptor CXCR2 are also widely reported to be elevated in CRC, the presence of which may facilitate CRC tumour progression." (PMID 21285972, 2011). "Transfection of CXCL1–3 into immortalised non-tumorigenic cells gave them the ability to form tumours." (PMID 21298036, 2011). "Comparison of the mean IRS scores for CXCR1, CXCR2 and CXCL1 in malignant and non-malignant tissue confirmed higher expression of each chemokine marker in the tumour epithelium relative to adjacent normal colorectal tissue." (PMID 21285972, 2011). "We examined if specific individual components of the tumour conditioned media (CCL2, CXCL1, CXCL5) could modulate dendritic cell maturation or cytokine secretion in response to LPS." (PMID 22125641, 2011). "For CXCL1 and TPT1, this tumor proliferative effect is already known." (PMID 19558675, 2009). "When antibodies specific for CXCL1, TPT1 or CD81 were added to tumor co-cultures with NPC, the suppressive effect by the NPC was significantly enhanced in several combinations of NPC and tumor, although to a varying extent." (PMID 19558675, 2009). "Therefore, the ability of DEX to suppress IL-8, CXCL1 and VEGF would appear to underpin an enhanced suppression of the tumour vasculature in the PC3 model of CRPC and potentiate the antiangiogenic effect of docetaxel." (PMID 19050703, 2008). "Moreover, ASC recruitment to PCa tumor cells and the TME may be brought about by the actions of CXCL1 and MCP produced by the cancer cells themselves." (PMID 41450167, 2026). "CXCL1 showed elevated expression in CRC tissues that correlated with more advanced clinicopathological features, such as larger tumor size, deeper invasion, the presence of lymph node metastasis, and higher clinical stage, thus is being considered a potential biomarker of tumor progression." (PMID 40943634, 2025). "VEGF and CXCL1 are potent proangiogenic factors, and their co-enrichment with TGF-β reinforces the notion that these vesicles could enhance vascular remodeling in the tumor stroma or at distant metastatic sites." (PMID 40943445, 2025).
tumor (continued). "In 2023, a team knocked down Malat1 RNA expression using gapmer ASOs and found that the levels of the chemokines CXCL1, GM‐CSF, and TNF‐α, which support MDSC recruitment, development, and immune suppression in the TME, were reduced, decreasing the number of PMN‐MDSCs in the tumor." (PMID 40452814, 2025). "Furthermore, the surface adhesin Fap2 of F. nucleatum can induce the secretion of pro-inflammatory cytokines IL-8 and C-X-C motif chemokine ligand 1 (CXCL1) and NOD-like receptor family pyrin domain containing 3 (NLRP3) activation to promote tumor migration and invasion." (PMID 39966840, 2025). "In addition, NF‐κB signalling could also induce the secretion of CXCL1 and the recruitment of CXCR2 + MDSCs into CRC tumours, thus impairing effective T cell responses during anti‐PD1 therapy." (PMID 40122703, 2025). "Additionally, metformin inhibits CXCL1 secretion in ESCC cells and tumor xenografts by enhancing AMPK phosphorylation and inducing the expression of the cell fate determinant Dachshund homolog 1 (DACH1), which subsequently leads to NF-κB inhibition and reduced MDSC migration." (PMID 40134607, 2025). "Blocking CXCL1 reduces the migration of MDSCs, TAMs, and Tregs to the tumor, thus significantly alleviates the highly immunosuppressive microenvironment of GBM and leads to the high aggregation of CD8+ T cells, thereby reactivating the anti-tumor immune response against GBM." (PMID 40527884, 2025). "Notably, a specific subtype of tumor cells enriched in tumor metastases are able to undergo EMT and further differentiate into growth-regulated oncogene-α-positive (CXCL1+) CAFs, which subsequently mature into secreted frizzled-related protein 2-positive (SFRP2+) CAFs." (PMID 41450739, 2025). "Overall, these findings demonstrate that ERO1α expression promotes tumor-suppressive microenvironment via recruitment and accumulation of PMN-MDSC cells mainly by facilitating proper protein folding of cytokines needed for recruitment of PMN-MDSC cells such as G-CSF, CXCL1 and CXCL2." (PMID 41226317, 2025). "Recent data from our group and others indicate that tumor cell–intrinsic factors in PDAC, such as CXCL1, EPHA2, USP22, EGFR, and the prostaglandin synthesis enzyme COX-2, promote myeloid cell infiltration that negatively impacts T cell infiltration, function, and tumor rejection." (PMID 39298269, 2024). "In contrast, in BCC, most cases do not show CXCL1 expression in the tumor." (PMID 38673949, 2024). "Smad4 acts as a tumor suppressor in CRC; however, the role of Smad4-mediated signaling in the immune microenvironment of CRC remains controversial Smad4 deletion in human CRC cells resulted in the recruitment of more neutrophils through the CXCL1/8-CXCR2 axis to promote CRC progression." (PMID 39664586, 2024). "Analysis of DB7 BCBM tumor lysates using a murine bio-plex cytokine panel showed that rHSVQ treatment induced secretion of chemokines attracting Ly6G + neutrophils/PMN-MDSCs, such as CXCL1, GM-CSF, IL-6, IL-10 and MCP1, which was significantly reduced by oHSV-D11mt treatment." (PMID 38853689, 2024). "Therefore, it was extremely necessary to determine whether CXCL1 and EGF could mediate crosstalk between OSCC cells and macrophages and further induce the aggressiveness of OSCC cells in the tumor microenvironment." (PMID 38713320, 2024). "Moreover, CXCR2 was also expressed on the macrophage surface and found to mediate tumor invasion and metastasis, so we hypothesized that OSCC cell-derived CXCL1 may promote macrophages to secrete EGF via CXCR2." (PMID 38713320, 2024). "Additionally, CXCL1 and CXCL2 have been shown to promote the resistance of HCC cells to sorafenib, whereas C-X-C motif chemokine receptor 2 inhibition induces reprogramming of the tumor immune environment that promotes immune checkpoint inhibition in MASH-HCC." (PMID 39621069, 2024).
tumor (continued). "Many previous studies have indicated that CXCL1 is highly expressed in the vast majority of OSCC cell lines and closely associated with OSCC invasion and metastasis, but the roles of tumor cell-secreted CXCL1 in the aggressiveness of OSCC have not been fully elucidated." (PMID 38713320, 2024). "Data from spleen show similar trend to breast between the untreated tumour and treated tissue, however the exception is that with the exception for PRF1 all other genes show higher expression in the verteporfin-PDT with BCL3 and CXCL1 showing the highest similar to that seen in breast tissue." (PMID 38022682, 2023). "Additionally, Fn creates a proinflammatory tumor milieu, which could induce CRC cells to upregulate the expression of IL-8 and CXCL1 and then recruit myeloid cells (mostly neutrophils) to the tumor." (PMID 37684625, 2023). "In addition, the decrease in CXCL1 and CXCL2 in tumor tissue induced by WGP may be related to MDSCs." (PMID 36713833, 2023). "The level of CXCL1 in the tumor is not related to the age of patients." (PMID 37108425, 2023). "Looking further, the overexpression of CXCL1 and CXCL2 was closely related to glioblastoma’s aggressiveness, facilitating the migration of myeloid cells and, simultaneously, disrupting the accumulation of CD8+ T-cells at the tumor site, thus instigating cancer progression." (PMID 36980182, 2023). "Furthermore, higher expressions of CXCL1, CXCL3, and CXCL8 in the high UVRAG expression group also indicated that UVRAG expression had a relationship with promoting tumor progression, angiogenesis, and immune suppression by recruiting tumor-associated macrophages (TMAs)." (PMID 37173968, 2023). "CXCL1 could bind to CXCR2 on MDSCs and promote their migration to the tumor microenvironment." (PMID 37865804, 2023). "In OSM-knockout mice, cSCC tumor volume was reduced by approximately 30% when compared to wild-type mice after one month, however there were still significant amounts of IL-6, IL-1β, IL-23α, CXCL1, IL-4, and IFNγ present in the tumor tissue compared to normal skin." (PMID 37841259, 2023). "In a cancer cell, CXCL1 expression may also be due to the interaction of this cell with other non-cancerous cells in the tumor niche." (PMID 37408240, 2023). "The level of CXCL1 expression is also not related to tumor size or histologic grade." (PMID 37108425, 2023). "Moreover, Western blot analysis showed that the CXCL1 protein was detected in tumor tissue from mice injected with rKLK6 only, but not in those from mice injected with the rKLK6/PAR1 inhibitor." (PMID 36552865, 2022). "Specifically, CXCL-1, IL-6, and IL-8 exhibit autocrine growth effects via stimulating proliferation of the cells they are produced in, and EGF, IL-1, and VEGF have been shown to display paracrine growth effects via modulating the tissue microenvironment to support tumor growth and progression." (PMID 36497078, 2022). "From this we could postulate that CCL17, CXCL1 and CCL2 act early and in a similar way to indirectly help tumour growth, possibly by upregulating CXCL10 production and myeloid cell expansion, which act more directly on tumour growth." (PMID 35226704, 2022). "Ddx5 was increased in the whole skin lesions of MC903- or IMQ-treated Cd93–/– mice compared with their wild-type counterparts, along with fewer plaques on the ears or dorsal skin and reduced expression of Il4, Il13, Ccl11, Ccl17 and Ccl22 or Cxcl1, Cxcl2, Ccl20, Il23, Il17a and Il36γ." (PMID 36271146, 2022). "Similarly, the INHBA+ macrophage subset co-expressed pro-tumorigenic molecules such as IL6, TGFβ, TIMP1, CCL20, CXCL1, and IL10, highlighting the highly plastic and complex nature of tumor-infiltrating myeloid cells in vivo, consistent with recent similar studies in other solid tumors." (PMID 36439171, 2022).
tumor (continued). "Besides, critical chemokine ligand family members (including CXCL1, CXCL2, CXCL5, CXCL8, and CXCL11), which involved in tumor growth regulation and metastasis and mediated the enrichment of CD8+ T cells into the TME, were upregulated in the high AI score subtype." (PMID 36245985, 2022). "In addition, the increased RNA and cytokine levels of CXCL1 and CXCL2 could be restored by ferrostatin-1 treatment, suggesting that cisplatin enhanced the expression levels of CXCL1 and CXCL2 expression via inducing ferroptosis of tumor cells." (PMID 35784745, 2022). "These receptors guide the migration of myeloid derived cells from the bone marrow to tumor regions where CXCL1 and CXCL2 are highly expressed, inhibit the activity and proliferation of effector T cells, and stimulate the growth of regulatory T cells, thereby promoting tumor immune escape." (PMID 34630121, 2021). "In ovarian cancer, Snail1 accelerates cancer progression via up-regulation of CXCL1 and CXCL2 as well as recruitment of myeloid-derived suppressor cells (MDSCs), which plays a vital role in cancer immunosuppression, tumor angiogenesis, drug resistance and promotion of tumor metastasis." (PMID 34917071, 2021). "However, CXCL1 was not detectable in 5 female and 14 male tumor tissues (19 patients in total), and CXCL2 was not quantifiable in tumor tissues of 3 female and 8 male patients (11 patients in total)." (PMID 34654834, 2021). "Due to this dramatic down-regulation in chemokine receptors’ expression on TANs, we hypothesized that the chemokines binding CXCR2 and CXCR4 (i.e., CXCL1/CXCL2 and CXCL12, respectively) could be responsible for the differential infiltration of NDN and LDN into the tumor." (PMID 34680231, 2021). "Our observations that CXCL1 and IL-8 are enhanced by the inclusion of stromal cells in 3D cultures of CRC cells and macrophages indicate that targeting the CXCR1/2 signalling axis may represent a therapeutic target in stromal-dense CRC tumours." (PMID 34885111, 2021). "Besides, the positive correlation of CXCL1 levels depends on the size of tumor, stage of advancing, and depth of invasion while negative to survival rate of patients has been reported." (PMID 34760697, 2021). "Importantly, some of the cytokines and chemokines upregulated in the tumor were also elevated in the plasma of mice receiving heterologous KV vaccine, including increased levels of IFN-γ, CCL5, CXCL10, CCL2, IL-6, CXCL1, and IL-1β one day after VSV-GP-HPV boost." (PMID 34465781, 2021). "While TRAIL expression on activated NK and T cells increases their cytotoxicity, CXCL1 induction of TRAIL on BCSCs can turn them into apoptosis inducers, which suppress neighbor cancer cells, but also T cell activation and proliferation, favoring tumor immune evasion." (PMID 34195201, 2021). "On the other hand, human tumor studies showed that chemokines such as CXCL1 and CXCL8 are produced by tumor cells, macrophages, and neutrophils to recruit further neutrophils, macrophages, and sometimes myeloid-derived suppressor cells (MDSC) where the MDSC would prevent the killing of tumor cells." (PMID 34437478, 2021). "In HCC tumor microenvironment, several cytokines and chemokines such as CXCL1, CSF1, CCL2, CCL9, IL-6, and IL-18 etc., which were secreted from either HCC cells or immune cells, promotes the recruitment and infiltration of MDSCs from the bone marrow into HCC tumor site 32-34." (PMID 33897880, 2021). "The gene expression of multiple inflammatory markers in the heart was significantly upregulated in tumor-bearing mice as compared to tumor-free mice, including the pro-inflammatory cytokines IL-1α, IL-1β, IL-6, and TNF- α and the inflammatory chemokines Mcp-1, Cxcl1, and Cxcl10." (PMID 34445729, 2021).